GSK3B (glycogen synthase kinase 3 beta)
Diseases named in the same sentence as GSK3B in open-access papers (continued):
Sharing a sentence is not in itself a finding about the gene and the disease.
neurodegenerative disease (156 papers, 2008 to 2026). A disorder of the central nervous system characterized by gradual and progressive loss of neural tissue and neurologic function. "Glycogen Synthase Kinase 3β (GSK-3β) is a key coordinator of neuronal development and maintenance; hyperactive GSK-3β is linked to neurodevelopmental and -degenerative diseases and therefore a promising therapeutic target." (PMID 41701831, 2026). "Reduced Beclin1 levels have been associated with neurodegenerative diseases, indicating that GSK3β’s regulation of proper autophagic function depends on Beclin1." (PMID 41190025, 2025). "GSK3β is strongly implicated in neurodegenerative diseases and is a negative regulator of the VAPB-PTPIP51 interaction." (PMID 40045432, 2025). "Over-expression of GSK-3β is also linked with the development of neurodegenerative diseases such as AD, ALS, and MS." (PMID 38367137, 2024). "GSK-3β overexpression has been found to inhibit neurogenesis and cause cellular death, while GSK-3β inhibitors are studied as promising therapeutics for neurodegenerative diseases." (PMID 39064687, 2024). "Their findings suggest that LPLI protects against STS-induced apoptosis by disrupting the Bax translocation process via the PI3K/Akt/GSK-3β pathway, making it a potential therapy for neurodegenerative diseases linked to GSK-3β activity." (PMID 39595827, 2024). "GSK3β phosphorylates the tau protein, hyperphosphorylated forms of which are associated with neurodegenerative diseases, including AD." (PMID 36834685, 2023). "GSEA assay showed that eIF4E2-GSK3β pathway was significantly associated with WNT signaling or neurodegenerative disease, both of which are highly related to GSK3β." (PMID 35568694, 2022). "GSK-3β is undoubtedly a relevant protein kinase that is associated with multiple pathways of neurodegenerative diseases, thus representing a promising therapeutic target addressed to drug candidates in this context." (PMID 34361017, 2021). "Glycogen synthase kinase-3 beta (GSK-3β) is an enzyme pertinently linked to neurodegenerative diseases since it is associated with the regulation of key neuropathological features in the central nervous system." (PMID 34361017, 2021). "In fact, the dysregulations of ERK and GSK3β have been found in a variety of in vitro and in vivo models associated with neurodegenerative diseases." (PMID 33955647, 2021). "Dysfunction of GSK3β has been implicated in a variety of neurodegenerative diseases, such as PD and AD." (PMID 32993098, 2020). "Dysregulation of GSK3β activity in neuronal cells has been implicated in the pathogenesis of neurodegenerative diseases." (PMID 32993098, 2020). "The inhibition of GSK‐3β via phosphorylation has been correlated with neuroprotection in brain injury, and GSK‐3β is implicated as a factor in Alzheimer's and other neurodegenerative diseases." (PMID 31960628, 2020). "It is important to consider that an upregulation of GSK-3β is linked to degradation of β-catenin and alterations in this signaling cascade have been reported to be related to the pathogenesis of neurodegenerative diseases." (PMID 30935413, 2019). "GSK3B is associated with a variety of tumors and neurodegenerative diseases and the inhibitor of GSK3B has the effect of remission on the mouse model of RA, showing an anti-inflammatory effect." (PMID 29848990, 2018). "A causal role for GSK-3, in particular the brain-enriched GSK-3β isoform, has been demonstrated in neurodegenerative diseases such as Alzheimer’s and Huntington’s, and in psychiatric diseases." (PMID 30237424, 2018). "Recent studies linked the interaction of PTPIP51/VAPB to the GSK3β activation status in a neurodegenerative disease, namely ALS." (PMID 28754031, 2017). "The protein tau, a substrate of GSK3β, interacts with microtubules and is associated with early memory loss and cognitive dysfunction in neurodegenerative diseases." (PMID 23082110, 2012).
neurodegenerative disease (continued). "GSK3β plays a diverse role in normal brain function, and its dysregulation is believed to underlie some psychiatric disorders and neurodegenerative diseases." (PMID 20111716, 2010). "Inactivation of Akt triggers GSK-3β activity through decreasing phosphorylation, which plays a key role in neuronal loss occurring in neurodegenerative diseases, such as PD and AD." (PMID 20540782, 2010). "The mild nature of these changes, however, makes it unlikely that differential effects of GSK-3β phosphorylation on the isoforms are causative in neurodegenerative disease." (PMID 19409104, 2009). "Similarly, Beclin-1, which plays a key role in autophagy initiation through complex formation with PI3K, is positively regulated upon GSK3β inhibition, restoring autophagic activity and reducing neuronal loss in neurodegenerative disease models." (PMID 41190025, 2025). "Taken together, over-expression of GSK-3β is linked with the development of different neurodegenerative diseases, and GSK-3β inhibitors could be a novel therapeutic strategy in the management of neurodegenerative diseases." (PMID 38367137, 2024). "In addition to a direct effect on glucose homeostasis, hippocampal GSK-3β activation has been associated with neurodegenerative diseases." (PMID 38344021, 2024). "GSK-3β is associated with cell survival and apoptosis, which can promote peripheral nerve regeneration, improve regrowth of synapses after peripheral nerve damage, and play a role in neurodegenerative diseases." (PMID 35592257, 2022). "As it inhibits several common pathogenic pathways in neurodegenerative diseases, GSK3β could be a potential target for the development of novel therapeutics for neurodegenerative diseases." (PMID 32993098, 2020). "Regulating GSK3β activity is a promising candidate for alleviating cognitive symptoms associated with psychiatric and neurodegenerative diseases, albeit how current pharmacological agents mediate their beneficial properties remains unclear." (PMID 29449801, 2018). "Furthermore, impaired GSK-3β activity has been associated with psychiatric disorders and neurodegenerative diseases, including AD." (PMID 27379018, 2016). "Therefore, extensive studies have focused on GSK-3β as a potential therapeutic target for neurodegenerative diseases associated with tau pathology." (PMID 25977830, 2015). "Moreover, GSK-3β is an enzyme involved in the formation of highly phosphorylated tau protein in neurofibrillary tangles (NFTs) and is also involved in neuronal loss in neurodegenerative diseases." (PMID 39199197, 2024). "Sex may be involved in the association results of GSK3B and neurodegenerative disease." (PMID 24779391, 2014). "Targeting GSK3β offers therapeutic promise for neurodegenerative diseases due to its crucial role in regulating autophagy proteins." (PMID 41190025, 2025). "This review is intended to analyze the function of GSK3β in autophagy regulation and its potential impact on neurodegenerative diseases." (PMID 41190025, 2025). "In neurodegenerative diseases, the GSK3β-protein interaction is crucial, as autophagy impairment contributes to toxic aggregate accumulation and neuronal death." (PMID 41190025, 2025). "Previous research has shown that the PI3K/AKT/GSK3β signaling pathway is critical in neuroinflammation and neurodegenerative diseases, particularly AD." (PMID 40869265, 2025). "Targeting GSK3β for autophagy modulation presents several challenges that can complicate therapeutic strategies in neurodegenerative diseases and other conditions." (PMID 41190025, 2025). "A better understanding of the pathways linking neurodegenerative disease insults to GSK3β activation, VAPB-PTPIP51 phosphorylation and binding would progress this important field." (PMID 40045432, 2025). "Modulation of GSK3β in brain is a major focus for treating neuropsychiatric and neurodegenerative diseases." (PMID 40084086, 2025).
neurodegenerative disease (continued). "Innovative small molecules targeting enzymes such as GSK-3β, which are involved in glycogen regulation, have also demonstrated efficacy in preclinical models of neurodegenerative diseases." (PMID 39997753, 2025). "Combining therapies that target GSK3β and autophagy pathways is a promising strategy for treating neurodegenerative diseases and other conditions." (PMID 41190025, 2025). "For example, inflammatory cytokines can activate GSK3β, leading to increased neuronal injury in neurodegenerative diseases." (PMID 41190025, 2025). "One pathway with a prominent role in neurodegenerative disease is the signaling pathway in which the GSK3β is a key component." (PMID 40251348, 2025). "Following an analysis of prediction results, we selected CDK5 and GSK-3β as potential target candidates for the investigated polyphenols, both kinases being involved in the physiopathology of neurodegenerative diseases and neuropathic pain." (PMID 38732407, 2024). "For these reasons, many studies have focused on the phytotherapeutic effects of antioxidant phenolic compounds that regulate the Akt/GSK-3β/tau pathway and improve neurodegenerative diseases such as AD." (PMID 38881175, 2024). "Findings from preclinical and clinical studies illustrated that exaggerated GSK-3β activity is involved in progressive neurodegeneration in different neurodegenerative diseases." (PMID 38367137, 2024). "Many efforts have been done for using of GSK-3β inhibitors in the management of neurodegenerative diseases including PD." (PMID 38367137, 2024). "Over-expression of GSK-3β is also interconnected with the development of different neurodegenerative diseases." (PMID 38367137, 2024). "Increased GSK3β activity and concomitant disruption of transport have been reported in neurodegenerative diseases suggesting that LMTK deficiency can potentially perturb GSK3β-associated signalling cascades regulating axonal transport." (PMID 39520508, 2024). "Nevertheless, exaggeration of GSK3β signaling pathway is intricate in the pathogenesis of AD and other neurodegenerative disease." (PMID 39719518, 2024). "Several GSK3β inhibitors are currently under investigation in preclinical and clinical studies to treat neurodegenerative diseases." (PMID 38755145, 2024). "GSK-3β is abundant in the central nervous system, and regulating GSK-3β activity is considered to be one of the important preventive strategies for neurodegenerative diseases." (PMID 39081851, 2024). "The finding that Nup358 regulates the ERMCSs through GSK3β opens up avenues to look into the possible mechanisms of how nucleoporin dysregulations impinge on multiple neurodegenerative diseases." (PMID 39026009, 2024). "GSK-3β is another critical player in neurodegenerative diseases, particularly due to its role in phosphorylating tau protein, leading to the formation of neurofibrillary tangles, a hallmark of AD." (PMID 39598743, 2024). "The dysregulation of FOX-family factor activity by insulin, mediated through the 3-phosphoinositide pathway and GSK3β, leads to neurodegenerative diseases and metabolic disorders." (PMID 36834685, 2023). "Nonetheless, downregulation of GSK-3β levels and modulation of the Wnt pathway are reported to be protective in many neurodegenerative diseases, including AD, which adds value to our study by using sesamol." (PMID 37601053, 2023). "GSK3β, a multifunctional serine/threonine protein kinase, is critically involved in the molecular pathology of many neurodegenerative diseases." (PMID 36293516, 2022). "Since GSK-3β has a crucial role in metabolism, insulin signaling, protein regulation, and inflammation, GSK-3β inhibition is considered an attractive target for therapeutic intervention in metabolic and neurodegenerative diseases." (PMID 35055183, 2022).
neurodegenerative disease (continued). "Meanwhile, investigations reveal that TMP analogs CXC195 and DT-010 protect dopaminergic neurons against apoptosis through the activation of PI3K/Akt/GSK3β signaling pathway in neurodegenerative disease models, including Parkinson’s Disease (PD) and AD." (PMID 34025340, 2021). "Deregulation of GSK3β is a critical step in the development and progression of neurodegenerative diseases via activation of neuroinflammatory processes." (PMID 33430188, 2021). "One of the most studied GSK-3β inhibitors is lithium, which is used as a pharmacological alternative to treat psychiatric disorders such as bipolar disorder as well as neurodegenerative diseases (e.g., AD and PD)." (PMID 34361017, 2021). "Glycogen Synthase Kinase-3β (GSK-3β) participates in several signaling pathways and plays a crucial role in neurodegenerative diseases, inflammation, and neuropathic pain." (PMID 32483472, 2020). "Inactive GSK3β has been shown to prevent apoptosis, and abnormal phosphorylation of GSK3 is thought to cause neurodegenerative diseases." (PMID 33233587, 2020). "It has been reported that the PI3K/mTOR/GSK3β signaling pathway participates in the regulation of various neurodegenerative diseases." (PMID 32832542, 2020). "In the research of neurodegenerative diseases and neuropsychiatric diseases, more and more researchers pay attention to GSK3β." (PMID 32832542, 2020). "In conclusion, sodium selenate enhances PP2A levels but acts through an alternate pathway to affect membrane potentials and dephosphorylate Tau and GSK3β with implications for therapies in neurodegenerative disease models." (PMID 30781361, 2019). "In the light of these findings, exploring the mechanisms of action of tideglusib (including GSK-3β inhibition and PPARγ activation) are important in terms of neurodegenerative diseases." (PMID 30965670, 2019). "According to in vitro and in vivo evidence concerning neurodegenerative diseases such as AD, GSK3β has a crucial role in memory impairment." (PMID 31640277, 2019). "Although most GSK3β protein is cytosolic, a small amount of GSK3β functions in mitochondria and the nucleus in patients with neurodegenerative diseases." (PMID 29515352, 2018). "GSK-3β inhibitors remain a potential new therapeutic drug for many neurodegenerative diseases, including ALS." (PMID 29082245, 2017). "Although several studies have reported that lithium and other synthetic GSK-3β inhibitors have promising neuroprotective effects on many neurodegenerative diseases, other studies have reported opposite results." (PMID 29082245, 2017). "GSK-3 exists as two isoforms, GSK-3α and GSK-3β, but the major research focus has been on GSK-3β as a result of its involvement in neuropsychiatric and neurodegenerative disease." (PMID 29375364, 2017). "Currently, there has been considerable effort directed towards GSK-3β as a potential target for the treatment of many diseases, including Type-II diabetes and neurodegenerative diseases." (PMID 29137141, 2017). "The neuroprotective effect was explained by the antiapoptotic effect of the GSK-3β inhibitor on the neurodegenerative disease." (PMID 29082245, 2017). "GSK-3 is a highly conserved serine/threonine protein kinase comprised of two isoforms such as GSK-3α and GSK-3β, which are glycogen synthase regulators and involved in several neurodegenerative diseases." (PMID 27552165, 2016). "Current therapeutic approaches to elevate the β-catenin level (such as GSK-3β inhibitor) in neurodegenerative diseases are in development." (PMID 27713508, 2016). "Increasing evidence has shed light on the role of GSK-3β in neurodegenerative diseases and on the fact that Aβ treatment results in increased GSK-3β activity in neuronal cells." (PMID 25089827, 2014). "GSK-3β is a multifaceted enzyme that has been indicated to be involved in the pathogenesis of neurodegenerative diseases, including PD, by modulating multiple signaling pathways." (PMID 24681994, 2014).
neurodegenerative disease (continued). "To evaluate a modulator of LTD, we decided to analyze GSK-3β, which is a key enzyme studied in neurodegenerative diseases and in the processes of plasticity and memory." (PMID 25524173, 2014). "Glycogen synthase kinase 3β (GSK3β) has emerged as one of the most attractive therapeutic targets for the treatment of neurodegenerative diseases, and GSK3β inhibitors have been successfully applied to the clinical practice for decades." (PMID 24312384, 2013). "Hence, GSK3β plays a pivotal role in the regulation of autophagy-related proteins, influencing the autophagic process and its implications in neurodegenerative diseases." (PMID 41190025, 2025). "Chronic inhibition of GSK3β may lead to long-term alterations in cellular signaling that could be detrimental, particularly in the context of neurodegenerative diseases where precise regulation of cellular processes is vital." (PMID 41190025, 2025). "In neurodegenerative diseases, a detrimental feedback loop may arise from the interplay between GSK3β and autophagy." (PMID 41190025, 2025). "The relationship between GSK3β and autophagy is highly relevant, given that defective autophagic processes can result in the accumulation of toxic protein aggregates and damaged organelles, hallmarks of neurodegenerative diseases." (PMID 41190025, 2025). "Furthermore, GSK-3β can promote the mitochondrial apoptotic pathway by increasing the Bax/Bcl-2 ratio, contributing to neurodegenerative diseases." (PMID 40166467, 2025). "Understanding the link between GSK3β and autophagy could inform the development of treatments for neurodegenerative diseases and other autophagy-related conditions." (PMID 41190025, 2025). "Hence, while targeting GSK3β for autophagy modulation holds significant promise for treating neurodegenerative diseases and other conditions, several challenges must be addressed." (PMID 41190025, 2025). "Modulation of TREM2 impacts the regulatory kinase GSK-3β, which has a distinct role in the pathogenesis of various neurodegenerative diseases, and is associated with the PI3K–AKT–GSK-3β–mTOR signaling axis, a critical pathway for cellular metabolism, growth, and proliferation." (PMID 41465422, 2025). "Assuming that PP1 and GSK3β are also transported to the synapse by the LMTK2-KLC-kinesin-1 motor complex, LMTK2 deficiency can induce further synaptic dysfunction in neurodegenerative diseases by disrupting axonal transport of these important synaptic signalling molecules." (PMID 39520508, 2024). "Therefore, loss of LMTK2 can contribute to microglia activation and neuroinflammation in neurodegenerative diseases by activating GSK3β and blocking the anti-inflammatory effect of Nrf2." (PMID 39520508, 2024). "Therefore, GSK-3β inhibitors which cannot cross BBB have limited efficacy in the management of neurodegenerative diseases." (PMID 38367137, 2024). "The abnormal activation of GSK-3β is closely related to aging and neurodegenerative diseases." (PMID 39451557, 2024). "Furthermore, MTOR and GSK3B are also being investigated as the potential targets for the therapeutic intervention of neurodegenerative diseases and aging." (PMID 36523604, 2022). "Finally, we expect that the results provided in this work will contribute to the development of new allosteric modulators of GSK-3β, which is a relevant kinase to be used as a target to treat neurodegenerative diseases." (PMID 34361017, 2021). "Only low cytotoxicities against human, bacterial, and fungal cell lines were observed, whereas the ningalins 183 and 184 showed moderate inhibition of the kinases CK1δ, CDK5, and GSK3β, potential targets for the treatment of neurodegenerative diseases (IC50 values between 1.6 μM and 10.9 μM)." (PMID 34564176, 2021).